MYBL2 (MYB proto-oncogene like 2)
Diseases named in the same sentence as MYBL2 in open-access papers (continued):
Sharing a sentence is not in itself a finding about the gene and the disease.
cancer (continued). "The dysregulation of above AS events in ATRX and MYBL2 are significantly related to mitosis and tumorigenesis in cancer patients, suggesting that MTA1 may regulate mitosis and tumorigenesis by targeting the AS of these two mitosis regulators." (PMID 32901005, 2020). "To further investigate whether any particular cancer-specific enhancers were linked to patient outcome, we performed survival analyses using cancer-specific enhancer probes linked to CENPA, FOXM1, or MYBL2." (PMID 32925947, 2020). "Expression of CENPA, FOXM1, and MYBL2 did not appear to be very strongly associated with age, sex, or cancer stage." (PMID 32925947, 2020). "Notably, the transcription factor MYBL2 is a central regulator of cell survival, proliferation and differentiation in cancer, and PLK1 and TOP2A are druggable by clinically advanced inhibitors." (PMID 32824422, 2020). "Tumor samples with higher expression of CENPA, FOXM1, and MYBL2 appear to harbor relatively more cancer-specific enhancers, suggesting that tumors highly expressing CENPA, FOXM1, and MYBL2 may have distinct enhancer profiles." (PMID 32925947, 2020). "Further, MYBL2 deregulations occurred in a broad spectrum of cancer entities." (PMID 31270369, 2019). "MYBL2 is a physiological regulator of cell cycle progression, cell survival and cell differentiation, but due to its frequently found deregulation in cancer, it significantly drives cancer initiation and/or progression." (PMID 28640249, 2017). "In this review, we summarize the physiological roles of MYBL2 in cell cycle regulation, cell survival and cell differentiation, and describe its deregulation as well as the resulting functional and clinical implications in cancer." (PMID 28640249, 2017). "Furthermore, we assessed gene expression in the 16 cancer types in which both A3B and MYBL2 were markedly upregulated (P < 0.001)." (PMID 28276478, 2017). "When deregulated in cancer cells, MYBL2 mediates the deregulation of these properties." (PMID 28640249, 2017). "Although no direct MYBL2 inhibitor is available yet, CDK2 inhibition could be used to reduce MYBL2 activity in MYBL2 high-expressing cancers." (PMID 28640249, 2017). "To explore whether B-Myb (Mybl2) is one factor in cancer cells contributing to enhanced arenavirus replication, we studied Mybl2 expression and phosphorylation in cancer tissues and non-malignant controls." (PMID 28248314, 2017). "Moreover, we found that signaling mediated by the epidermal growth factor receptor (EGFR) participates in MYBL2 and A3B expression in cancer cells." (PMID 28276478, 2017). "As expected, A3B expression correlated with that of MYBL2 in 15 of the 16 cancer types." (PMID 28276478, 2017). "MYBL2 and players of its downstream transcriptional network can be used as prognostic and/or predictive biomarkers as well as potential therapeutic targets to offer less toxic and more specific anti-cancer therapies in future." (PMID 28640249, 2017). "Therefore, our results indicate that FCGR2A, PDE3A, and EPPK1 are the main target genes for MYBL2 and may function as novel cancer biomarkers." (PMID 35664780, 2022). "The three non-imprinted genes at 20q11-q13.32 examined in our study, AURKA, MYBL2, and ZNF217, have a strong influence on cell cycle, proliferation, signaling, survival, and differentiation of malignant cells and on cancer progression, and they have been implicated in cancer drug resistance." (PMID 36461044, 2022).
cancer (continued). "However, additional agents involved in the MYBL2 downstream transcriptional network mediating its cancer-promoting properties remain unclear; furthermore, it is unknown which additional cancer entities are also affected by MYBL2 deregulation." (PMID 35664780, 2022). "However, MYBL2 in regulation of cancer metabolism is rarely investigated." (PMID 36494680, 2022). "Therefore, circ-MYBL2 may suppress the role of miR-19a in inhibiting cancer cell proliferation and metastasis." (PMID 35387554, 2022). "Therefore, we examined the subgroup of LUAD samples, which had high expression of the three transcriptional regulators as well as many enhancer links (over 290 cancer-specific CENPA, FOXM1, or MYBL2 enhancer links), called “highly linked” samples for correlations to overall patient survival." (PMID 32925947, 2020). "Similarly, MYBL2 is a transcription factor which promotes cell proliferation and differentiation by fostering cell cycle entry into S and M phases, and is dysregulated in types of cancer." (PMID 32660466, 2020). "Therefore, MYBL2 and/or players of its downstream transcriptional network could serve as effective targets for cancer treatment." (PMID 28640249, 2017). "In contrast, the upregulated gene set (e.g., SIM2, MYBL2, HJURP) was overexpressed in up to 22 cancers, indicating an oncogenic-like role and participation in common tumor-promoting pathways." (PMID 41439026, 2025). "The RCC score includes a panel of 12 genes, with 7 cancer-related genes (stromal genes: INHBA, BGN, and cell cycle genes: MKI67, MYC, MYBL2, GADD45B) and 5 reference genes, and is used to predict CRC recurrence." (PMID 40664638, 2025). "Of note, the CDK4/6 inhibitor palbociclib, which is clinically used in adjuvant cancer therapy, reduced the expression of E2F1, MYBL2, and FOXM1 and of endoreduplications." (PMID 40319068, 2025). "MYB proto-oncogene like 2 (MYBL2), a transcription factor belonging to the MYB family, plays a crucial role in regulating the cancer cell cycle progression, cellular survival, and differentiation." (PMID 40092688, 2025). "Among the genes closely related to SPSB2 expression, CDC45, RAD51, TRIP13, MYBL2, and CDC20 play essential roles in cancer development." (PMID 40149497, 2025). "Among these potential targets, two oncogenes, MYBL2 and RAD54L, which were previously demonstrated to be targets of E2F145–49, were downregulated in both cancer cell lines upon NSUN2 knockdown." (PMID 38424195, 2024). "This study found that in cancer types with over 12 tumor and para-cancer tissues, the genes RRM2, TK1, CCNB1, DLGAP5, CCNA2, MYBL2, and HJURP were repeatedly overexpressed across various cancer tissues." (PMID 39669580, 2024). "Within this cluster, we found a high expression of the proto‐oncogene MYBL2, as well as of CGGBP1, which regulates the cell cycle in cancer cells." (PMID 39167619, 2024). "Among these are enhancers for JUP, MYBL2, and CCNE1, and we show that their activity is required for cancer cell viability." (PMID 36803948, 2023). "So, MYBL2 regulated purine anabolism, which meant it was also in control of GTP, influencing beyond biomasses synthesis, of great important in cancer cell proliferation." (PMID 36494680, 2022). "Transcription factors, including Sp1, AP-2, BRCA, E2F1 and MYBL2, bind to the DNA sequence in the promoter region of RRM2 and regulate their expression in response to DNA damage in cancer cells." (PMID 35651787, 2022). "It has been reported that MALAT1 regulates cancer metabolism and the Warburg effect via the mTOR pathway in HCC, and also regulates MYBL2 expression level in HCC by affecting the alternative splicing of its pre-mRNA." (PMID 35557985, 2022).
cancer (continued). "The expression levels of MYBL2, RBL1, LIN9, and E2F5 in various cancers were significantly upregulated." (PMID 35664326, 2022). "To validate our approach, we also examined the expression level of MYBL2 and SCARA5 genes, which are reported to be upregulated and downregulated in cancer, respectively." (PMID 33805806, 2021). "MYBL2 can help DNA double-strand repair in hematopoietic stem cells and the emergence of CNV leads to the occurrence and development of cancer." (PMID 33985534, 2021). "Immunohistochemical staining was performed for AXIN2, MYBL2, TGFBI, and SLC35D3, which represented that the part of cancer was deeper than that of normal." (PMID 35174154, 2021). "Since no significant expression changes of TAF15 existed between the cancer and normal tissues of CRC, probably MYBL2 dominated the S-phase RRM2 transcription in the complex in CRC cells." (PMID 34234118, 2021). "Its short isoform behaved as a putative tumor suppressor through regulating the expression of MYB proto-oncogene like 2 (MYBL2) and played an important role in the cell cycles and cancer relapse and drug resistance." (PMID 34616428, 2021). "Three clinically significant and highly studied genes were selected as target genes for each cancer type: HERE2, MYBL2, and MMP11 for BRCA and NOTCH2, BRCA1, and PDC for COAD." (PMID 34422018, 2021). "However, MYBL2 and ORC1 hadn’t been reported whether associated with cancer stemness." (PMID 34266348, 2021). "RNA-seq data from the Cancer Cell Line Encyclopedia (CCLE) was used to identify MYBL2 High and MYBL2 Low cell lines." (PMID 33489883, 2020). "The subgroups include proliferation genes (Ki67, STK15; Survivin, CCNB1, MYBL2), invasion genes (MMPP11, CTSL2), HER2 genes (GRB2, HER2), estrogen genes (ER, PGR, BCL2, SCUBE2), and other cancer related genes (GSTM1, CD68, BAG1)." (PMID 33665165, 2020). "This suggests that although some cancer-specific enhancers are common to LUAD and BRCA, the enhancers regulated by CENPA, FOXM1, and MYBL2 are largely different between tumor types." (PMID 32925947, 2020). "We identified consistently upregulated genes (such as E2F1, EZH2, FOXM1, MYBL2, PLK1, TTK, AURKA/B and BUB1) and consistently downregulated genes (such as SCARA5, MYOM1, NKAPL, PEG3, USP2, SLC5A7 and HMGCLL1) across various cancers." (PMID 28427185, 2017). "Candidate oncogenes, ZNF-217, CYP24A1, MYBL2 and AIB2, encompassing the region analyzed by FISH, were previously reported to be amplified in other types of cancer as well." (PMID 17311676, 2007). "This evidence was supported by a reduction in cell proliferation in cancer cell lines having MYBL2 overexpression without proving apparent mechanisms." (PMID 35887528, 2022). "The cancer genes are composed of genes that code for HER2 (HER2 and GRB7), oestrogen genes (ER, PGR, BCL2, and SCUBE2), proliferation genes (MKI67, STK15, BIRC5, CCNB1, and MYBL2), and invasion genes (MMP11 and CTSL2) as well as GSTM1, CD68, and BAG1." (PMID 36042999, 2022). "In addition, 9 of the 18 GII-specific core regulators were annotated to cell cycle pathway, such as MYBL2, FOXM1, previously known to be related to cancer abnormal cell cycle." (PMID 34001209, 2021). "Interestingly, the genes CDC20, CDCA8, MYBL2, C1QTNF6, CEP55, CDK1 and KIF14 were found to be more universal/common, since they mark multiple types of cancers not only in prognosis but also in diagnosis." (PMID 32489468, 2020). "A study found that high expression MYBL2 gene disrupts the DREAM complex and increase the MMB complex formation and subsequently triggers the expression of the several target genes driving the cell proliferation in cancer." (PMID 31681566, 2019). "It has been proposed that MYBL2 might mediate EMT and cancer cell invasion by upregulates the expression of major EMT regulator SNAIL in breast cancer." (PMID 29321541, 2018).
cancer (continued). "MYBL2 (V-Myb avian myeloblastosis viral oncogene homolog-like 2), a transcription factor of the MYB family of transcription factors, contributes to these properties of a cancer cell." (PMID 28640249, 2017). "Indeed, of the eight CRC GWAS loci found within this subset of CRC-related smoking genes, CDCA8, CDKN3, FADS1, FADS2, MYBL2, PCSK9, and PRC1, have all been reported to be overexpressed in others cancers and to play important roles in the DNA damage response pathway." (PMID 37509213, 2023). "Finally, immunohistochemistry (IHC) staining showed that the protein expressions of both MYBL2 and RRM2 were significantly upregulated in the cancer tissues compared to their paired normal tissues in our cohort of 69 CRC patients with a strong correlation coefficient between their expression levels." (PMID 34234118, 2021). "In addition, the pan-cancer network contains the TFs FOXM1 and MYBL2 which support our finding." (PMID 31681566, 2019). "Interestingly, this analysis revealed that the MYB mRNA level was strongly reduced in the basal cancer subtype, and those of MYBL1 and MYBL2 increased, compared to the levels in normal tissue, partially in line with our finding that p95HER2 expression shifts the miRNA profile towards this subtype." (PMID 30833639, 2019). "For example, in the seven cancer types (BLCA, ESCA, HNSC, KIRC, LIHC, STAD and UCEC) with both grade phenotype information and normal control samples, expression of AURKB, BUB1, FOXM1, HMMR, MYBL2, and PLK1 follows the pattern in five cancer types (BLCA, HNSC, KIRC, LIHC, and UCEC)." (PMID 28427185, 2017). "As expected, the tumor sample population showed higher expression levels of pro-mitotic genes such as CCNB1 and MYBL2, genes that modulate the host immune response, such as SERPINB3, and the tight-junctions proteins claudin-4 and claudin-6, which are often deregulated in cancers." (PMID 27542596, 2016). "FOS, JUN and MYBL2 are partly known to play a role in cancer, but not explicitly in MCL." (PMID 18416826, 2008). "The results indicated that the expression levels of MYBL2 and RRM2 were significantly higher in cancer tissues compared to adjacent non-cancerous tissues." (PMID 40885709, 2025). "In addition to imprinted genes, the 20q11-q13.32 chromosomal region contains multiple non-imprinted genes involved in cancer, e.g., AIB3, AIB4, AURKA (STK6), BTAK, MYBL2, PTPN1, STK15, and ZNF217." (PMID 36461044, 2022). "We therefore examined the total number of cancer-specific enhancer links in samples with and without KRAS or EGFR genetic alterations and in the highest quartile and remaining quartiles of expression of FOXM1 and MYBL2, respectively." (PMID 32925947, 2020).
tumor (154 papers, 2007 to 2026). "CENPA and MYBL2 have been implicated in cell cycle regulation and transcriptional control and have been linked to aggressive tumor growth." (PMID 41402347, 2025). "MYBL2 demonstrated dynamic interactions with the tumor immune microenvironment, including associations with immune cell infiltration patterns and co-expression with immune checkpoint molecules and chemokines." (PMID 40432915, 2025). "MYB proto-oncogene like 2 (MYBL2) has been identified as a potential target gene implicated in tumor progression." (PMID 40092688, 2025). "Despite receiving BCMA/CS1 dual-target CAR-T therapy, the patient's tumor continued to progress, failing to suppress extramedullary relapse, while the poor prognosis was potentially associated with increased MYBL2 expression levels." (PMID 39844819, 2025). "In PCa, MYBL2 was linked to tumor cell plasticity and adaptation of tumor cells to androgen deprivation, but also to aggressive hormone-sensitive PCa84–86." (PMID 41402347, 2025). "CDK2 inhibition phenocopied genetic loss of Mybl2 and significantly decreased in vivo tumor growth associated with enrichment of DNA damage." (PMID 39113611, 2024). "Loss of Mybl2 expression significantly reduced the potential for overall in vivo tumor formation and growth." (PMID 39113611, 2024). "Aberrant expression of MYBL2 contributes to tumor malignancy and is associated with poor patient prognosis." (PMID 35664780, 2022). "In the LC&OC network, eleven DEGs of the LCI network were also coexpressed, suggesting that most of the LC&OC network DEGs and MYBL2 are associated with the progression of tumor pathology." (PMID 36101460, 2022). "Our previous analysis of TCGA data supported our cellular model by showing that MYBL2 undergoes gene copy number gain in the majority of HGSOC tumor samples and, in turn, is associated with increased expression of DREAM and MMB target genes." (PMID 33747961, 2021). "While dysregulated MYBL2 expression has been linked to genomic instability and poor outcomes in multiple carcinomas, including lung, the pro-tumor transcriptional programs regulated by MYBL2 have remained elusive." (PMID 33489883, 2020). "The median values for mutation load and MYBL2 expression from exomic and transcriptomic sequence data, respectively, were calculated for each tumor type." (PMID 28276478, 2017). "Transcription of Mybl2 and Mycn, markers for neoplastic growth and tumor susceptibility, paralleled Pou5f1 expression and decreased as the cardiac program progressed." (PMID 18184438, 2008). "Consequently, we extended our investigation to assess MYBL2 expression across various tumor types and its association with immune infiltration." (PMID 40092688, 2025). "CDK2 inhibition phenocopied genetic loss of Mybl2 and significantly reduced tumor growth." (PMID 39113611, 2024). "Additionally, a notable positive association was observed between MYBL2 expression and tumor mutational burden (TMB), a predictive indicator for response to PD1 antibody treatment." (PMID 38947375, 2024). "Moreover, SP2 was lowly expressed in tumor tissues and associated with a good prognosis, while MYBL2 was highly expressed in tumor tissues and associated with a poorer prognosis." (PMID 37638005, 2023). "Moreover, we confirmed the mutated status of the newly identified MYBL2 (V-Myb avian myeloblastosis viral oncogene homolog-like 2) gene in our patient tumor sample." (PMID 32742192, 2020). "Here we identify MYBL2, which encodes a transcription factor with functions in checkpoint control of the G2 cell cycle phase, as a key tumor suppressor gene in over one half of all MDS cases, whether characterized by a 20q deletion or a normal karyotype." (PMID 23878725, 2013). "Our findings establish a clear regulatory link where MYBL2 is a direct and functionally important target of the tumor-suppressive miR-29a." (PMID 42065054, 2026).